USP8 (ubiquitin specific peptidase 8)
Diseases named in the same sentence as USP8 in open-access papers (continued):
Sharing a sentence is not in itself a finding about the gene and the disease.
ovarian carcinoma (4 papers, 2022 to 2025). A malignant neoplasm originating from the surface ovarian epithelium. "Of note, USP8 is overexpressed in various cancer types and in ovarian cancer it is associated with poor prognosis." (PMID 39430244, 2024). "We assessed the levels and activity of the USP8 protein in different ovarian cancer cell lines including three cisplatin-resistant variants (IGROV-1/Pt1, A2780/CP and A2780/BBR), established by chronic exposure to platinum drugs, using western blot analysis." (PMID 36578788, 2022). "Taken together, our results support that USP8 may be of diagnostic value and may provide a therapeutic target to improve the efficacy of platinum-based therapy in ovarian carcinoma." (PMID 36578788, 2022). "To define the possible clinical relevance of our preclinical results, we also carried out an exploratory IHC analysis of USP8 in ovarian carcinoma clinical samples." (PMID 36578788, 2022). "To explore the role of USP8 in the clinical setting in ovarian carcinoma, we carried out IHC staining on 65 clinical specimens from advanced stage ovarian carcinoma." (PMID 36578788, 2022). "Thus, we used ovarian carcinoma cells of different histotypes, including cisplatin-resistant variants with increased survival features to evaluate the efficacy of molecular targeting of USP8 as a strategy to overcome drug resistance/modulate cisplatin response." (PMID 36578788, 2022). "Our findings show that molecular targeting of USP8 in ovarian carcinoma cells results in improved apoptotic response to cisplatin." (PMID 36578788, 2022). "Coughlin and colleagues reported that the USP8 inhibitor RA-9 selectively promotes apoptosis in ovarian cancer cell lines and primary culture cells, and that its mechanism of action is related to an unfolded protein response activated against a proteotoxic stress." (PMID 39430244, 2024). "Indeed, knockdown of USP8 in ovarian cancer cells produces a downregulation of the anti-apoptotic action of FLIPL associated with enhanced susceptibility to cisplatin-induced apoptosis resulting from enhanced caspase 3/7 activation." (PMID 39430244, 2024). "Immunohistochemical staining on 65 clinical specimens from advanced stage ovarian carcinoma indicated that 40% of tumors were USP8 positive suggesting that USP8 is an independent prognostic factor for adverse outcome when considering progression free survival as a clinical end-point." (PMID 36578788, 2022). "When we examined USP8 expression levels and activity in different ovarian carcinoma cell lines including pairs of cisplatin sensitive and resistant cells, we found increased levels in the latter and enhanced activity in cells representative of the endometrioid ovarian carcinoma subtype." (PMID 36578788, 2022). "With this approach, we identified that a large subset of ovarian carcinomas were USP8 positive." (PMID 36578788, 2022). "There are more studies on identifying important DUBs such as USP8 and USP19 in ovarian cancers." (PMID 37107644, 2023). "In this regard, USP8 has been reported to counteract apoptosis mediated by death receptors by increasing the stability of FLIPS95 and this is consistent with enhanced cisplatin-induced activation of caspase 8 following USP8 knockdown in ovarian carcinoma cells." (PMID 39430244, 2024).
somatotroph tumors (4 papers, 2022 to 2025). "So far, few genes have been identified as drivers for PitNETs, such as GNAS in somatotroph tumors and USP8 in corticotroph tumors." (PMID 40523964, 2025). "Most PitNETs are without known mutations, with some exceptions: GNAS (somatotroph tumors), USP8 (corticotroph tumors), and ATRX (corticotroph tumors)." (PMID 39388031, 2024).
inflammatory bowel disease (3 papers, 2022 to 2023). A spectrum of small and large bowel inflammatory diseases of unknown etiology. "A study showed that mice with specific deletion of USP8 + T cells exhibited dysfunctional Tregs and inflammatory bowel disease, which suggested that USP8 might be associated with T cell function." (PMID 36539510, 2023). "Importantly, USP8 has been identified as an immunomodulatory DUB as T-cell-specific Usp8 deficiency disrupts regulatory T-cell functions, leading to recruiting abundant CD8+ γδT cells in colons and resulting in inflammatory bowel disease in mice." (PMID 35361799, 2022).
intrahepatic cholangiocarcinoma (3 papers, 2024 to 2025). A carcinoma that arises from the intrahepatic bile duct epithelium in any site of the intrahepatic biliary tree. "Meanwhile, DUB-IN3, the USP8 inhibitor, could also restrain the malignancy of intrahepatic cholangiocarcinoma." (PMID 38973004, 2024). "Furthermore, it has been reported that targeting USP8 with DUB-IN-3, a specific inhibitor of USP8, could suppress the progression of HCC and intrahepatic cholangiocarcinoma (iCCA)." (PMID 40862294, 2025). "Our research has also found that USP8 stabilizes OGT through deubiquitination, thereby promoting the progression of intrahepatic cholangiocarcinoma (ICC)." (PMID 40607251, 2025).
liver fibrosis (3 papers, 2021 to 2025). "In conclusion, here we showed that the METTL3/MALAT1/PTBP1/USP8/TAK1 axis was activated in macrophages during the development of liver fibrosis." (PMID 34839365, 2021). "The signaling cascade METTL3/MALAT1/PTBP1/USP8/TAK1, by essentially stimulating pyroptosis and inflammation of macrophages, aggravates liver fibrosis." (PMID 34839365, 2021). "In KCs isolated from in vivo liver fibrosis model or in vitro M1-polarized macrophages, METTL3 was up-regulated, and sequentially, it increased MALAT1 level via m6A methylation, which promoted USP8 mRNA degradation through the interaction with PTBP1." (PMID 34839365, 2021). "In addition, the METTL3/MALAT1/PTBP1/USP8/TAK1 axis in liver fibrosis promotes pyroptosis and macrophage M1 polarization, thereby exacerbating liver fibrosis progression." (PMID 37063421, 2023).
lung adenocarcinoma (3 papers, 2019 to 2023). A carcinoma that arises from the lung and is characterized by the presence of malignant glandular epithelial cells. "In addition, USP8 expression was correlated with EGFR mutation status and patients who had USP8-positive lung adenocarcinoma had significantly poorer outcomes than those who were USP8-negative." (PMID 34081623, 2021). "Prof. Masayuki Noguchi’s team identified that SFN specifically binds to ubiquitinated protease 8 (USP8) in lung adenocarcinoma cells, enhancing the stabilization of receptor tyrosine kinases (RTKs), including EGFR and MET, through abnormal regulation of USP8." (PMID 37398672, 2023). "Furthermore, they found that SFN enhances receptor tyrosine kinases stabilization by aberrant ubiquitin-specific protease 8 (USPB) regulation in lung adenocarcinoma, implying that SFN could be an appropriate therapeutic target for lung adenocarcinoma than USP8." (PMID 30926680, 2019).
viral infection (3 papers, 2021 to 2025). "Viral infection promotes the phosphorylation and activation of USP8 in an AKT‐dependent manner, which in turn increases the expression of MDA5 and, consequently, its antiviral ability." (PMID 40525588, 2025). "To further investigate how USP8 enzyme activity is regulated during viral infection, we performed an in vitro DUB assay." (PMID 40525588, 2025). "Viral infections indirectly prevent MDA5 proteasome-degradation by activating USP8 via AKT-dependent." (PMID 40963624, 2025). "In fact, viral infections boost USP8 activation via AKT-dependent phosphorylation, increasing MDA5 expression." (PMID 40963624, 2025). "It is found that viral infection modulates the AKT‐dependent phosphorylation of USP8 at serine 718, which not only promotes the activation of USP8 but also enhances the association between USP8 and MDA5 and the consequent deubiquitination and stabilization of MDA5." (PMID 40525588, 2025). "In addition, we did not observe any association of USP8 expression with patients’ clinicopathology, such as disease stage and virus infection status." (PMID 34081623, 2021).
acromegaly (2 papers, 2020 to 2023). Acromegaly is an acquired disorder related to excessive production of growth hormone (GH) and characterized by progressive somatic disfigurement (mainly involving the face and extremities) and systemic manifestations. "Hotspot variants in GNAS and USP8 are the most common genetic causes of acromegaly and Cushing’s disease, respectively." (PMID 38067388, 2023).
autoimmune disease (2 papers, 2025). A disorder resulting from loss of function or tissue destruction of an organ or multiple organs, arising from humoral or cellular immune responses of the individual to their own tissue constituents. "In brief, these findings reveal specific roles of USP8 in the innate antiviral immune response and autoimmune diseases via the deubiquitination and stabilization of MDA5." (PMID 40525588, 2025). "Pharmacological inhibition of USP8/AKT alleviates MDA5‐driven autoimmunity, demonstrating the USP8‐MDA5 axis as a therapeutic target for autoimmune disorders linked to aberrant MDA5 activation." (PMID 40525588, 2025). "The authors conclude that USP8 inhibition could provide potential treatment for autoimmune diseases, by redirecting MDA5 to degradation and, in turn, inhibiting overactive type-I and -III IFN activation." (PMID 40963624, 2025). "Interestingly, treatment with the USP8 inhibitor significantly reduced the protein levels of MDA5 and p‐TBK1 in PBMCs, suggesting that USP8 could be a promising therapeutic target for treating MDA5‐related autoimmune diseases." (PMID 40525588, 2025).
Autoimmunity (2 papers, 2025). The occurrence of an immune reaction against the organism's own cells or tissues. "Blocking the activities of USP8 or AKT effectively suppressed MDA5‐induced autoimmunity in AGS mice and MDA5+ DM/SLE patient cells." (PMID 40525588, 2025). "Importantly, inhibition of USP8 or AKT can effectively suppress MDA5‐induced autoimmunity in Aicardi–Goutières syndrome (AGS) mice and anti‐MDA5‐positive dermatomyositis (DM)/systemic lupus erythematosus (SLE) patient cells." (PMID 40525588, 2025). "Taken together, our findings not only reveal the detailed mechanism by which the MDA5 protein homeostasis is modulated but also suggest that inactivation of USP8 or AKT may be an effective strategy for the treatment of autoimmunity related to MDA5, regardless of the type of mutation." (PMID 40525588, 2025). "Here, it is shown that inactivation of ubiquitin‐specific protease 8 (USP8/UBPy) degrades the MDA5 protein, suppressing antiviral signaling and autoimmunity." (PMID 40525588, 2025). "USP8 inhibition allows MDA5 ubiquitination and proteolysis, preventing its overactivation and providing a potential target to impair autoimmunity development." (PMID 40963624, 2025).
ciliopathy (2 papers, 2018 to 2020). A genetic disorder of the cellular cilia or the cilia anchoring structures, the basal bodies, or of ciliary function. "These in vivo studies support the in vitro finding that USP8 functions to suppress ciliogenesis and suggest that malfunction of USP8 cause ciliopathy through elongation of cilia." (PMID 29472535, 2018). "Using CRISPR/Cas9, we generated usp8 knockout (KO) zebrafish, which displayed various ciliopathy-related phenotypes, including cystic kidney, hydrocephalus, and microphthalmia." (PMID 29472535, 2018). "We further found that usp8 knockout zebrafish developed ciliopathy-related anomalies, suggesting that USP8 functions as an important factor of ciliogenesis in vertebrates." (PMID 29472535, 2018). "We further show that usp8 knockout zebrafish develops ciliopathy-related phenotypes including cystic kidney, suggesting that USP8 is a regulator of ciliogenesis in vertebrates." (PMID 29472535, 2018). "Because AURKA is also associated with both cancer and ciliopathy, these findings suggest that the involvement of KCTD17 and USP8 in cancer and ciliopathy might be mediated by effects on ciliogenesis via a TCHP–AURKA pathway." (PMID 32825105, 2020). "The most frequent ciliopathy-related phenotype observed in usp8 KO was cystic kidney." (PMID 29472535, 2018). "Next, we aimed to assess whether USP8 is involved in ciliary regulation in vivo and in ciliopathy conditions." (PMID 29472535, 2018). "Moreover, usp8 knockout zebrafish displays the ciliopathy-related phenotypes." (PMID 29472535, 2018).
cognitive deficits (2 papers, 2025 to 2026). "Functional validation in murine models shows that USP8 overexpression rescues LPS-induced cognitive deficits and motor coordination impairment, whereas USP8 depletion exacerbates neuroinflammatory damage." (PMID 40529211, 2025).
Cushing syndrome (2 papers, 2016 to 2023). Cushing's syndrome (CS) encompasses a group of hormonal disorders caused by prolonged and high exposure levels to glucocorticoids that can be of either endogenous (adrenal cortex production) or exogenous (iatrogenic) origin. "Moreover, somatic mutations in the Usp8 and Usp48 genes have frequently been observed in patients with Cushing syndrome, suggesting regulatory roles of these USPs in energy metabolism." (PMID 36834633, 2023). "We also performed NGS sequencing of all USP8 CDs in ten samples with enough genetic material and were able to exclude also the possibility that mutations in other regions outside the 14-3-3 binding site of the USP8 gene may be involved in the canine pituitary-dependent hyperadrenocorticism." (PMID 28005997, 2016).
cystic kidney (2 papers, 2018 to 2021). "Our conclusion is supported by the data of usp8 KO zebrafish, in which cystic kidney occurs in ~40% of the KO animals." (PMID 29472535, 2018). "The relatively high incidence of cystic kidney in usp8 KO zebrafish is well concordant with the unifying theory." (PMID 29472535, 2018). "Given that usp8 KO in zebrafish also increases ciliation in the pronephric duct, these findings suggest that increased degradation of TCHP and subsequent inhibition of AURKA may be involved in the ciliation and cystic kidney defects observed in animals with NDEL1 or USPS8 KD." (PMID 34944109, 2021).
glioma (2 papers, 2022 to 2023). A benign or malignant brain and spinal cord tumor that arises from glial cells (astrocytes, oligodendrocytes, ependymal cells). "Recently, there are emerging studies using the CRISPR/Cas9 method in glioma, by which researchers have been able to identify several members responsible for glioma cell growth and proliferation such as USP8 and SOCS3." (PMID 35586564, 2022). "The USP8 inhibitor DUB-IN-1 effectively reduced the percentages of cells with positive Ki-67 staining, suggesting a growth-suppressive influence of USP8 inhibition on these glioma cells." (PMID 36816802, 2023). "After confirming the inhibitory effects of pharmacological USP8 inhibition on glioma cell growth and stemness, we performed transcriptomic profiling of LN229 and T98G cells with or without USP8 inhibitor DUB-IN-1 treatment to investigate its underlying mechanisms." (PMID 36816802, 2023).
Hypertension (2 papers, 2022 to 2023). The presence of chronic increased pressure in the systemic arterial system. "It has been shown that USP2-45 and USP8 can reverse the binding of the E3 ubiquitin protein ligase Nedd4-2 to epithelial Na+ channels, which in turn affects Na+ transport and uptake, which are closely associated with hypertension." (PMID 36845374, 2023). "Here, we found the significant association of ADM, EDN1, ANGPTL4, USP8, NFIL3, MSR1, and CEBPD genes with hypertension." (PMID 35205232, 2022). "Therefore, we proposed that USP8 target drug therapies will play a vital role in hypertension treatment." (PMID 35205232, 2022). "ADM, EDN1, ANGPTL4, NFIL3, MSR1, CEBPD, and USP8, based on their FDR values (<0.05, p-values (≤0.05)), were the top DEGs for hypertension." (PMID 35205232, 2022). "From 50 DEGs, we ranked 7 hypertension-related genes (p-value < 0.05): ADM, ANGPTL4, USP8, EDN, NFIL3, MSR1, and CEBPD." (PMID 35205232, 2022).
leukemia (2 papers, 2020 to 2021). A malignant (clonal) hematologic disorder, involving hematopoietic stem cells and characterized by the presence of primitive or atypical myeloid or lymphoid cells in the bone marrow and the blood. "Also, other deubiquitinases, such as USP2, USP8, USP10 and USP42, fuse with leukemia-associated genes, indicating that deubiquitinases play an important role in the pathogenesis of AML." (PMID 34454635, 2021). "Targeting USP2/USP8 may be important to improve the outcomes of MLL-rearranged leukemia." (PMID 34454635, 2021). "Until now, USP2, USP8, and USP10 have been found to be fused with MLL, which indicates that DUBs may be potential targets of MLL-r leukemia." (PMID 34454635, 2021).
liver failure (2 papers, 2019 to 2021). A liver disease characterized by the liver losing or has lost all of its function. "USP8 knockout (KO) mice exhibit early embryonic lethality while induced deletion in adult animals rapidly causes lethal liver failure." (PMID 31845722, 2019). "Studies on USP8-knockout (KO) mice have revealed that USP8 is involved in liver failure and immune cell maintenance." (PMID 33919439, 2021).
prostate carcinoma (2 papers, 2022 to 2025). A carcinoma that arises from epithelial cells of the prostate gland. "Thereby, it is needed to carry on the experiment in docetaxel-resistant prostate cancer in vitro and in vivo to establish USP8 as a therapeutic target for not only prostate cancer but also docetaxel-resistant prostate cancer." (PMID 36338727, 2022). "In contrast, overexpression of USP8 resulted in strong proliferative effects, suggesting that USP8 functions as an oncogene in prostate cancer growth, survival, and metastasis." (PMID 36338727, 2022). "Prostate cancer (PCa) is the most diagnosed malignancy among men, but USP8’s role in PCa is not yet investigated comprehensively." (PMID 36338727, 2022).
renal carcinoma (2 papers, 2019 to 2023). A carcinoma arising from the epithelium of the renal parenchyma or the renal pelvis. "To clarify the role of piR-1742 in the malignant progression of renal cancer, we performed RNA sequencing analysis on A498 and ACHN cell lines after treatment with the piR-1742 inhibitor, and we found that the mRNA level of USP8 was significantly decreased." (PMID 37332045, 2023).